PDX1 (pancreatic and duodenal homeobox 1)
Diseases named in the same sentence as PDX1 in open-access papers (continued):
Sharing a sentence is not in itself a finding about the gene and the disease.
insulinoma (continued). "Furthermore, the extract upregulated PDX-1 gene expression, contributing to increased gene transcription of insulin-like growth factor 2 (IGF-2) and insulin in INS-1 cells (rat insulinoma cell line, a β-cell line)." (PMID 34335803, 2021). "As expected, the majority of insulinomas expressed PDX1, except one malignant and one DAXX/ATRX mutated insulinomas, which showed nuclear positivity for ARX but not for PDX1." (PMID 33288854, 2020). "We determined protein expression of ARX and PDX1 together with ATRX, DAXX, ARID1A, and H3K36me3 by immunohistochemistry, as well as ALT and CDKN2A deletions by fluorescence in situ hybridization (FISH), in a cohort of clinically defined sporadic insulinomas." (PMID 32103422, 2020). "A key unanticipated finding is that the 19 insulinomas differ from the five beta-cell data sets with regard to the methylation status of the INS region, where the key beta-cell transcription factor, PDX1, binds, recruits other enhancer members, and transactivates INS gene expression." (PMID 33060578, 2020). "Differential expression of UCH-L1, MAP1B, MAP2, VCAN, CDK4 and PDX-1 was verified in more than 40 PNETs, including insulinomas and non-insulinomas by IHC but the expression of CaSR was only validated in 29 insulinomas." (PMID 28526880, 2017). "Since there are no residual insulinoma cells found in this model after therapy, the islet data demonstrate the ability of the systemically-delivered treatment to knockdown PDX-1 in this model." (PMID 22905092, 2012). "However, non-metastatic insulinomas tend to express PDX1, a specific transcription factor of islet β cells." (PMID 37251916, 2023). "Whether the ARX and PDX1 transcription factors play a role in the clinical behavior of insulinomas is not known." (PMID 32103422, 2020). "Out of the six insulinomas, four were positive for ARX and negative for PDX1, one was negative for ARX and positive for PDX1, and for one sample the immunohistochemistry was not available." (PMID 41212394, 2025). "Of note, two insulinomas and the glucagonoma were ARX positive and PDX1 negative, as assessed by immunohistochemistry." (PMID 41212394, 2025). "Of interest, whereas typical small insulinomas show strong PDX1 expression but no ARX expression (as seen in normal beta-cells), aggressive insulinomas also express ARX (lacking in normal beta-cells, but present in alpha- or gamma-cells)." (PMID 39331358, 2024). "A portion of metastatic insulinomas were largely derived from non-metastatic insulinomas in hormone secretion and ARX/PDX1 expression patterns." (PMID 37251916, 2023). "For these four patients, the proinsulin/insulin molar ratio <1 and primary tumors were all present as PDX1+, ARX-, and insulin+, which were similar to non-metastatic insulinomas." (PMID 37251916, 2023). "Canonical beta cell transcription factors such as PDX1, NKX6.1, MAFA, and others were not substantially altered in insulinomas vs. beta cells." (PMID 28974674, 2017).
pancreatic ductal adenocarcinoma (37 papers, 2011 to 2025). An infiltrating adenocarcinoma that arises from the epithelial cells of the pancreas. "Here, we found that increased plasma levels of endotoxin and bile acids in Pdx1-Cre: LSL-KrasG12D/+ mice were associated with the transformation of the pancreatic ductal carcinoma (PDAC) state." (PMID 35326559, 2022). "As a less hemorrhagic model, we utilized the KrasLSL-G12D;p53LoxP;Pdx1-CreER (KPC) orthotopic model of pancreatic ductal adenocarcinoma (PDAC) reported to result in spontaneous liver metastasis." (PMID 40482194, 2025). "In the pancreatic progenitor subtype of pancreatic ductal adenocarcinoma, however, PDX1 is expressed in precursor lesions that precede tumorigenesis and metastasis." (PMID 36272648, 2022). "To study the role of miR-301a in pancreatic ductal adenocarcinoma precursor formation, we crossed miR-301a−/− mice with Pdx1-Cre;KrasG12D mice." (PMID 35211358, 2022). "For instance, PDX1 is a key regulator in pancreatic development and β-cell function and meanwhile dynamically regulates pancreatic ductal adenocarcinoma initiation and maintenance." (PMID 32850410, 2020). "p16flox/flox; LSL-KrasG12D; Pdx1-Cre mice developed the full spectrum of pancreatic intraepithelial neoplasia (mPanIN) lesions, pancreatic ductal adenocarcinoma (PDA), and metastases were observed in all the mice." (PMID 22113502, 2011). "Indeed, ectopic expression of PDX1 inhibits cell proliferation in gastric cancer and specific stages of Kras-driven pancreatic ductal adenocarcinoma." (PMID 36272648, 2022). "An LSL-KrasG12D/−-Pdx-1-Cre mouse model of pancreatic ductal adenocarcinoma (PDAC) was created to study the effects of using four-week multi-strain probiotics (Lactobacillus paracasei GMNL-133 and Lactobacillus reuteri GMNL-89) as an adjuvant therapy for controlling cancer progression." (PMID 33230218, 2020). "For this purpose, we used conditional null alleles of Palb2 (Palb2flox2-3), Brca1 (Brca1flox2) and Brca2 (Brca2flox3-4) in combination with the well characterized Pdx1-Cre transgene that has been extensively used for modeling pancreatic ductal adenocarcinoma (PDAC) in mice." (PMID 31877165, 2019). "Recent studies have demonstrated overexpression of PDX1 and alterations in HES1 expression not only in ductal pancreatic adenocarcinoma, but also in cholangiocarcinoma and biliary intraepithelial neoplasia." (PMID 27829047, 2016).
pancreatic ductal adenocarcinoma (continued). "Furthermore, we observed significant inverse correlation between NEDD4L and ULK1 levels in the pancreatic regions from spontaneous pancreatic ductal adenocarcinoma (PDAC) mouse model driven by KrasLSL-G12D/+; Trp53LSL-R172H/+; Pdx1-Cre (KPC)." (PMID 31959741, 2020). "We next sought to explore the activity of dual node targeting in Kras mutant genetically engineered mouse (GEM) models, including a pancreatic ductal adenocarcinoma (PDAC) model (LSL-KrasG12D/+; p16/p19fl/fl; Pdx1-CRE) and a NSCLC model (LSL-KrasG12D/+;p53frt/frt)." (PMID 28982154, 2017).
Insulin resistance (24 papers, 2013 to 2025). Increased resistance towards insulin, that is, diminished effectiveness of insulin in reducing blood glucose levels. "Our previous study indicates m6A-regulated loss of Pdx1+ cells leads to decreased β-cell mass with implications on the ability to compensate for insulin resistance." (PMID 39322760, 2024). "Pdx1 is implicated in compensatory β cell mass expansion in response to diet-induced insulin resistance." (PMID 36574297, 2023). "For example, DNA hypermethylation of the beta cell Pdx1 gene was increased in a rat model of placental insufficiency, causing decreased Pdx1 gene expression levels; these changes were associated with insulin resistance and DM." (PMID 33668810, 2021). "The loss of FOXO1 and PDX1 transcription factor signaling in pancreatic β-cells, which results in the loss of insulin production prevalent in pathological conditions such as insulin resistance and T2DM, has been broadly demonstrated and identified as a key clinical target 1,40,41." (PMID 40585255, 2025). "Therefore, pathogenic variants in PDX1 may disturb mytochondiral function, contributing to β-cell failure, insulin resistance, and diabetes." (PMID 36361703, 2022). "The importance of this AKT/FOXA2/PDX1 axis in adaptation of β-cells to insulin resistance is only observed in conditions of reduced mTORC1 activity." (PMID 37423392, 2023). "We suggest that Raptor levels are critical to maintaining PDX1 levels and β-cell function in conditions of insulin resistance in male mice." (PMID 37423392, 2023). "Contrarily, Igf-induced β-cell proliferation was shown to be blocked in two models of insulin resistance, where the presence of the mutant Foxo1 transgene is retained in the nucleus and thus inhibits the expression of PDX1." (PMID 36361703, 2022). "Accordingly, downregulating PDX1 expression in humans and in animal models results in T2D, β-cell dysfunction, and impaired islet compensation in the presence of insulin resistance." (PMID 32093016, 2020). "Unlike hyperplasia driven by systemic insulin resistance, this finding, paired with the modest glucose intolerance, suggests an early adaptive remodeling phase in response to the PDX1 point mutation." (PMID 41199860, 2025). "Experimental study shows that sEVs from bone marrow stem cells increase the gene expression of insulin signal pathway (insulin, Pdx1, Smad2, Smad3, and transforming growth factor β) in the type 1 diabetes condition and alleviate insulin resistance in the T2D rat model." (PMID 37593852, 2023). "A maternal HFD induced insulin resistance and deterioration of pancreatic β-cell function in adult offspring at 20 weeks of years, accompanied by decreased insulin content and pancreatic homeobox 1 (PDX-1) mRNA levels in isolated islets." (PMID 32607287, 2020). "Further, beta cell hypertrophy contributes to beta cell compensation in high fat diet-induced insulin resistance and the master beta cell transcription factor, pancreatic duodenal homeobox 1 (Pdx1), regulates beta cell size, i.e., Pdx1 influences beta cell hyper- or hypotrophy." (PMID 23542897, 2013). "According to our analysis, most studies consistently reported differential DNA methylation that affected PDX-1, GLP1R, PPARGC1A, etc., and thus led to insulin resistance." (PMID 37201099, 2023). "In addition, Pdx1 also regulates the expression of GLUT2, both of which play a role in insulin resistance." (PMID 23894285, 2013). "Finally, these studies also reveal that increasing FOXA2 levels in islets with reduced mTORC1 activity rescue PDX1 levels and insulin secretion, highlighting the importance of the AKT/FOXA2/PDX1 axis as a possible therapeutic tool to improve β-cells in conditions of insulin resistance." (PMID 37423392, 2023). "While PDX1 expression itself is not induced by stress, it regulates islet compensation for HFD-induced insulin resistance, in part through direct transcriptional regulation of Atf4 and Wsf1." (PMID 32093016, 2020).
Glucose intolerance (22 papers, 2011 to 2025). Glucose intolerance (GI) can be defined as dysglycemia that comprises both prediabetes and diabetes. "It binds the insulin gene promoter, facilitating its transcription in response to varying glucose levels and loss or mutations of PDX1 are known to impair this process causing glucose intolerance." (PMID 41199860, 2025). "DNA methylation of the pancreatic and duodenal homeobox factor-1 (Pdx1) promoter of intrauterine growth retardation rats is considered a major cause of susceptibility to glucose intolerance in adulthood." (PMID 25658116, 2015). "Total pancreas inactivation of Vhlh using a Pdx-1-Cre (pancreatic and duodenal homeobox gene-1 promoter) transgenic mouse line causes glucose intolerance, similar to what has been observed in mice with deletion of Vhlh in ß-cells, but no other pancreatic abnormalities are observed." (PMID 23977255, 2013). "Mice with Vhlh loss in ß-cells exhibit glucose intolerance, and the reduced expression of maturity markers led us to hypothesize that the perinatal lethality observed in Pdx-1-Creearly;VhlhLoxP/LoxP mice might result from perturbed glucose homeostasis due to compromised cellular function." (PMID 23977255, 2013). "On the other hand, heterozygous carriers of PDX1 mutations are linked to MODY4, characterized by modest glucose intolerance due to compromised insulin secretion." (PMID 38333726, 2023). "Glucose intolerance observed in the Trpm7R/R mice on the HFD was consistent with the metabolic phenotype of Pdx1+/– animals." (PMID 36574297, 2023). "Inactivation of PI3K/Akt in β-cells has decreased insulin secretion and glucose intolerance through downregulating PDX-1." (PMID 35408495, 2022). "Mice heterozygous for Pdx1 develop glucose intolerance, increased apoptosis, decreased mass and abnormal islet architecture." (PMID 34638652, 2021). "While homozygous, β-cell specific EZH2 deficiency in RIP-Cre;Ezh2f/f or Pdx1-Cre;Ezh2f/f mice induces mild glucose-intolerance and reduced β-cell mass; heterozygous Pdx1-Cre;Ezh2f/+ mice display increased β-cell mass." (PMID 33137873, 2020). "Consistent with previous data Pdx1.tTA knock-in mice used in our study remain healthy aside from glucose intolerance thereby phenocopying the mild disease form observed in some MODY4 patients." (PMID 31682591, 2020). "Consistent with that, IKK2-DNPdx1 mice showed pronounced glucose intolerance compared to Pdx1+/− mice." (PMID 31682591, 2020). "In mature beta cells, depletion and reduction of PDX1 induces glucose intolerance, which suggests the critical role of PDX1 in maintaining beta cell function." (PMID 29096722, 2017). "Beta-cell specific PPARγ knockout mice exhibit glucose intolerance, impaired GSIS and deficiency in basal Pdx1 expression, as well as loss of sensitivity to the pharmacological effect of TZDs in enhancing Pdx1 expression." (PMID 23424659, 2013). "PAK1 plays an unforeseen and beneficial role in beta cells by promoting insulin biogenesis via enhancing the expression of PDX1, NEUROD1 and INS, along with anti-apoptotic effects, that culminate in increased insulin content and beta cell mass in vivo and ameliorate diet-induced glucose intolerance." (PMID 39404845, 2025). "However, SIRT6 regulates glucose sensing in pancreatic β cells, and by suppressing SIRT6, in pancreatic β-cells, forkhead box protein O1 (FOXO1) is deacetylated and pancreatic and duodenal homeobox 1 (PDX1) and GLUT2 expression is diminished inducing systemic glucose intolerance." (PMID 35008779, 2021).
type 1 diabetes (21 papers, 2014 to 2026). "For instance, EVs derived from menstrual blood MSCs enhance beta‐cell regeneration and function in a rat model of Type 1 diabetes (T1D) through a mechanism involving the PDX1 protein." (PMID 41584930, 2026). "The well-characterized MALAT1 has been shown to impair β cell function by reducing H3 histone acetylation at the PDX-1 promoter, thereby suppressing PDX-1 expression and insulin secretion, a critical mechanism in the development of type 1 diabetes." (PMID 40149464, 2025). "DJC effectively ameliorated oxidative stress in type 1 diabetic rats, with the expression of PDX-1 protein increased markedly." (PMID 26819084, 2016). "Whether interactions between CHD3, CHD4 with PDX1 are compromised in other β-cell stress conditions, for example, during type 1 diabetes progression, remains to be established." (PMID 41282155, 2025). "Nilotinib, a potent tyrosine kinase inhibitor member, and polyphenol recover the pancreatic β-cell function through the increase of antioxidant defense system and decrease of oxidative stress as well as the increase of PI3K/Akt/PDX-1 signaling in STZ-induced type 1 diabetic rat models." (PMID 41189666, 2025). "However, the effects of oat flakes on glycemic variability, dyslipidemia, and pancreatic duodenum homeobox-1 (PDX-1) levels in type 1 diabetes (T1D) remain unclear." (PMID 42280445, 2026). "Similarly, expressing the transcription factors Pdx1 and MafA in neighboring α cells can convert these cells into functional, insulin-producing β cells that appear resistant to autoimmune destruction in models of type 1 diabetes." (PMID 36706177, 2023). "Introduction of lentiviral PDX-1 significantly induces hAMSCs to differentiate into islet-like cell aggregates, which may provide a source of adipose stem cells-derived insulin-producing cells for cell replacement therapy in type 1 diabetes." (PMID 26082830, 2015).